SLC39A1 (solute carrier family 39 member 1)
Diseases named in the same sentence as SLC39A1 in open-access papers (continued):
Sharing a sentence is not in itself a finding about the gene and the disease.
gastric adenocarcinoma (3 papers, 2015 to 2023). "Aberrant high-SLC39A1 expression can serve as an independent unfavorable prognostic factor for gastric adenocarcinoma." (PMID 36407082, 2022). "Considering the clinical relevance of SLC39A1 in gastric adenocarcinoma, we next conducted survival analyses of our retrospective cohort using Kaplan–Meier method." (PMID 36407082, 2022). "Compared with adjacent stomach tissues, gastric adenocarcinoma tissues showed significantly higher SLC39A1 on both mRNA and protein levels." (PMID 36407082, 2022). "SLC39A1 is upregulated in gastric adenocarcinoma and plays oncogenic functions by promoting tumor growth and metastasis." (PMID 36407082, 2022). "By immunohistological staining, we found that SLC39A1 was lowly expressed in adjacent stomach tissues, while highly stained in the gastric adenocarcinoma specimen." (PMID 36407082, 2022). "A retrospective gastric adenocarcinoma cohort (n = 154) was collected from our hospital to test their tissue expression of SLC39A1 through immunohistochemical staining method." (PMID 36407082, 2022). "As for the detailed tumor-related functions, our in vitro and in vivo data proved that SLC39A1 overexpression can promote gastric adenocarcinoma proliferation, while SLC39A1 knockdown suppressed tumor growth." (PMID 36407082, 2022). "Univariate (P=0.001) and multivariate analyses (P=0.035) confirmed the independent prognostic significance of SLC39A1 on gastric adenocarcinoma outcomes." (PMID 36407082, 2022). "Importantly, SLC39A1 was also validated as a novel independent prognostic biomarker for gastric adenocarcinoma (hazard ratio 1.732, 95% confident interval 1.041-2.881, P=0.035)." (PMID 36407082, 2022). "Interestingly, Desouki and his colleagues reported that SLC39A1 showed lower expression in gastric mucinous carcinoma than that of gastric adenocarcinoma." (PMID 36407082, 2022). "Besides analyzing the mRNA level of SLC39A1 in the samples from online database, we enrolled an independent cohort of gastric adenocarcinoma patients from our hospital (n = 154)." (PMID 36407082, 2022). "Therefore, further studies will be invaluable to investigate whether SLC39A1 can regulate immune microenvironment of gastric adenocarcinomas." (PMID 36407082, 2022). "Here, we first compared the different expression of SLC39A1 between gastric adenocarcinoma tissues and nontumorous stomach tissues." (PMID 36407082, 2022).
renal carcinoma (3 papers, 2021 to 2025). A carcinoma arising from the epithelium of the renal parenchyma or the renal pelvis. "SLC39A1 caused significant disturbances in metabolic pathways in renal cancer cells and altered transcriptional and translational levels of 71 genes." (PMID 36407113, 2022). "In this paper, we performed comprehensive analysis based on data form transcriptomics, proteomics and metabolomics and found significant several altered metabolism and signal transduction pathways in SLC39A1-overexpressed renal cancer cells." (PMID 36407113, 2022). "Amino acid Metabolism was also altered: SLC39A1 decreased methionine, spermidine in renal cancer cell." (PMID 36407113, 2022). "Furthermore, the overexpression of solute carrier family 39 member 1 (SLC39A1) in renal cancer cells, specifically in the OSRC‐2 cell line, resulted in a significant downregulation of Lac‐Phe levels." (PMID 40534243, 2025). "Overall, we suggested that tumor angiogenesis in renal cancer cell could be inhibited by SLC39A1 through downregulating ANGPTL4, and inactivated PPAR signal pathway was the underlying mechanism." (PMID 36407113, 2022). "In our work, transcriptomics, proteomics, and metabolomics studies were performed on human renal cancer cell (OSRC-2) samples, composed of cells transfected with the negative control virus (NC) and SLC39A1 lentivirus (ZIP), aiming to identify key alteration arising from SLC39A1 in RCC." (PMID 36407113, 2022).
renal cell carcinoma (3 papers, 2022 to 2025). "Our work drew a comprehensive blueprint for the underlying mechanism through which SLC39A1 suppresses renal cell carcinoma progression and provided novel insight into the development of therapeutic targets and potential biomarkers for this disease." (PMID 36407113, 2022). "Previous study showed that SLC39A1 impaired tumor metabolism and regulated ell proliferation, migration, and cell cycle through the PPAR crosstalk regulation in renal cell carcinoma (RCC)." (PMID 37041476, 2023).
choriocarcinoma (1 paper, 2022). An aggressive malignant tumor arising from trophoblastic cells. "Moreover, DisGeNET analysis results demonstrated remarkable changes were caused by SLC39A1 in genes associated with complement Factor I (C3 inactivator) deficiency, ischemic stroke, choriocarcinoma and hypertensive disease." (PMID 36407113, 2022).
chronic obstructive pulmonary disease (1 paper, 2022). A chronic and progressive lung disorder characterized by the loss of elasticity of the bronchial tree and the air sacs, destruction of the air sacs wall, thickening of the bronchial wall, and mucous accumulation in the bronchial tree. "Dysregulated expression of SLC39A1 was reported to be correlated with multiple disorders, including short stature, chronic inflammation, and chronic obstructive pulmonary disease (COPD)." (PMID 36407082, 2022).
congenital disorder of glycosylation (1 paper, 2022). Congenital disorder of glycosylation (CDG) is a fast growing group of inborn errors of metabolism characterized by defective activity of enzymes that participate in glycosylation (modification of proteins and other macromolecules by adding and processing of oligosaccharide side chains). "In addition, the human metabolome database (HMDB) enrichment analysis revealed SLC39A1 also possessed noticeable impact on spermidine and spermine biosynthesis, lactose biosynthesis, GLUT-1 deficiency syndrome and congenital disorder of glycosylation CDG IId." (PMID 36407113, 2022).
diffuse large B-cell lymphoma (1 paper, 2024). "Our analysis demonstrated significant overexpression of SLC39A1 in brain lower grade glioma (LGG), lymphoid neoplasm diffuse large B-cell lymphoma (DLBC), glioblastoma multiforme (GBM), testicular germ cell tumors (TGCT), thymoma (THYM), LIHC, and PAAD." (PMID 38230214, 2024).
Dystonia (1 paper, 2025). An abnormally increased muscular tone that causes fixed abnormal postures. "Our analysis showed dystonia-parkinsonism predominates in SLC6A3 and PLA2G6, while GLB1, SLC30A10, and SLC39A1 show predominantly dystonic phenotypes with a low frequency of parkinsonism." (PMID 40362326, 2025).
tumor (31 papers, 2005 to 2026). "Apart from regulating tumour cells, elevated SLC39A1 expression is linked to the enhanced presence of Th2 cells but reduced infiltration of cytotoxic cells, contributing to adverse clinical prognoses in HCC." (PMID 40462487, 2025). "Research on HCC has shown that SLC39A1 overexpression is linked to immune infiltration and promotes tumor progression." (PMID 38053842, 2023). "In other words, given the advanced tumors tended to express lower SLC39A1, the expression of SLC39A1 was negatively associated with the malignant tendency of the tumor." (PMID 34615436, 2021). "However, the underlying mechanism through which SLC39A1 inhibited tumor progression remained unclear." (PMID 36407113, 2022). "Besides, decreased SLC39A1 expression was revealed to be associated with tumor differentiated degree, OS event and RFS event." (PMID 34615436, 2021). "Nude mice bearing subcutaneous tumours were used to investigate the role of SLC39A1 on tumour growth in vivo." (PMID 40462487, 2025). "Consistent with the in vitro result, the knockdown of SLC39A1 attenuated tumour progression, including reduced tumour weight, tumour‐to‐body weight ratio and tumour volume, while body weight was barely changed." (PMID 40462487, 2025). "Beyond ZIP10, other ZIPs contribute to tumorigenesis: SLC39A1 is upregulated in gastric adenocarcinoma and acts as an oncogene by promoting tumor growth and metastasis, whereas upregulated SLC39A7 promotes cell growth and survival through the Akt/mTOR pathway." (PMID 41583444, 2025). "Liver‐specific deletion of SLC39A1 strongly reduced number of tumours in DEN‐CCL4 models compared with SLC39A1f/f mice." (PMID 40462487, 2025). "Consistently, after excision, the tumor volume was significantly smaller in the SLC39A1-knockdown group and larger in the SLC39A1-overexpression group." (PMID 36407082, 2022). "In contrast, in vivo tumor growth was significantly suppressed in the SLC39A1-knockdown group, while it was accelerated in the SLC39A1-overexpression group." (PMID 36407082, 2022). "In other words, transwell experiments implied that SLC39A1 participates in tumor metastasis, which was consistent with clinical finding that SLC39A1 was positively correlated with lymph node metastasis." (PMID 36407082, 2022). "Our previous studies found that the depletion of SLC39A1 promoted tumor proliferation and invasion in RCC." (PMID 36407113, 2022). "Solute carrier 39A1 (SLC39A1) is an indirect zinc transporter which showed diverse tumor-related functions in different malignancies." (PMID 36407082, 2022). "Higher SLC39A1 was observed in patients with larger tumor size (P=0.003) and advanced tumor stages (P < 0.001)." (PMID 36407082, 2022). "High SLC39A1 is critical for a more aggressive tumor phenotype by promoting cell proliferation and invasion." (PMID 36407082, 2022). "Knocking down SLC39A1 remarkably promoted tumor proliferation and invasion ability and miR-223 was responsible for the dysregulation of SLC39A1 in RCC." (PMID 36407113, 2022). "One study showed that in an in vivo xenograft model, the overexpression of the SLC39A1 leads to an increased zinc uptake, reducing the tumor growth." (PMID 34925450, 2021). "The results showed that expression of SLC39A1 was correlated with OS in male patients (P = 0.003) and patients with young age (≤60) (P = 0.013), poorly differentiated tumor (P = 0.007) and clinical stage 1 (P = 0.012)." (PMID 34615436, 2021). "Although SLC39A1 is expressed widely in mammalian tissues, the tumor-related role of this transporter has been only established in the prostate." (PMID 34615436, 2021). "After the analysis of 90 EHCC cases, we found that the sections with low and moderate SLC39A1 expression accounted for a majority of tumor tissues." (PMID 34615436, 2021). "We then investigated the anti‐tumour effect of SLC39A1 specific peptide in vivo." (PMID 40462487, 2025).
tumor (continued). "The high zinc level may have specific crosstalk with SLC39A1, therefore shows specific tumor-related functions." (PMID 36407082, 2022). "The present study illustrated that SLC39A1 functioned as a tumor suppressor in RCC." (PMID 36407113, 2022). "Taken together, our data suggested that SLC39A1 may suppress tumor proliferation, migration, and cell cycle by interfering PI3K/AKT and cAMP/Epac pathway in RCC cells." (PMID 36407113, 2022). "Also, Tspo, a gene related to neuronal damage and increased inflammation interacts with Slc39a1, a regulator of immune responses and tumor malignant progression." (PMID 36614117, 2022). "As a candidate tumor suppressor, SLC39A1 may be a promising biomarker for early diagnosis, tumor progression, and prognostic assessment by IHC staining." (PMID 34615436, 2021). "In addition, subgroup analysis for RFS showed that the expression of SLC39A1 was associated with RFS in male patients (P = 0.012) and patients with young age (P = 0.032) and poorly differentiated tumor (P = 0.033)." (PMID 34615436, 2021). "Overall, we assumed that SLC39A1 was dys-regualted in EHCC compared with para-tumor tissues and might act as a potential prognostic biomarker." (PMID 34615436, 2021). "Therefore, we used the ESTIMATE algorithm to estimate tumor stroma cell and immune cell infiltration scores, and calculated the correlation between them and SLC39A1 expression." (PMID 33292262, 2020). "Therefore, we speculate that SLC39A1 facilitates cytotoxic T cells and reduces Th2 cell infiltration by elevating cellular Zn2+ levels, which finally forms a tumour‐promoting microenvironment." (PMID 40462487, 2025). "However, whether Zn2+ was an indispensable intermediary in the process of SLC39A1 inhibiting tumor progression remained to be explored." (PMID 36407113, 2022). "Moreover, overexpressing SLC39A1 may affect tumor immunity in HCC, as indicated by the enhanced infiltration of Th2 cells and impaired infiltration of cytotoxic cells." (PMID 36407082, 2022). "We analyzed the expressions of SLC39A1, SLC50A1 and SLC66A3 across tumour stages from Stage I to Stage IV in the TCGA database." (PMID 40462487, 2025). "PTBP1 and SLC39A1, which were overexpressed and indicated poor prognosis in LGG patients, were selected as tumor-specific antigens for LGG patients." (PMID 36307882, 2022). "In conclusion, we identified PTBP1and SLC39A1, and MMP9 and SLC16A3 as tumor specific antigens for LGG and GBM, respectively." (PMID 36307882, 2022). "Therefore, SLC39A1 may play an important role in tumor progression." (PMID 33292262, 2020). "More importantly, liver tissues from relapsed patients presented higher levels of SLC39A1 than non‐relapsed patients, regardless of adjacent or tumour tissue." (PMID 40462487, 2025). "Intriguingly, compared with adjacent tissues, SLC39A1 expression was significantly higher in the tumour tissues no matter in nonrelapsed or relapsed HCC patients." (PMID 40462487, 2025). "This also explained our finding that Zn2+ is not involved in SLC39A1‐regulated pro‐tumour activity in hepatocytes." (PMID 40462487, 2025). "In TCGA datasets, both DRP1 and SLC39A1 exhibited elevated expression in tumour tissues as opposed to normal tissues." (PMID 40462487, 2025). "Meanwhile, the mRNA expression of PTBP1 and SLC39A1 was significantly negative related to tumor purity (PTBP1, r = − 0.15; SLC39A1: r = − 0.61; P < 0.05)." (PMID 36307882, 2022). "And the mRNA expression of MMP9 and SLC16A3 was significantly negative related to tumor purity (PTBP1, r = − 0.53; SLC39A1: r = − 0.58; P < 0.05)." (PMID 36307882, 2022).
cancer (21 papers, 2015 to 2026). A tumor composed of atypical neoplastic, often pleomorphic cells that invade other tissues. "In addition, BASP1-AS1, RHOC and SLC39A1 have been reported to be associated with cancer." (PMID 37239411, 2023). "To investigate the associations between the expression of SLC39A1, SLC39A4, and SLC39A8 and immune infiltration in related cancers, we utilized the TIMER database." (PMID 38230214, 2024). "The analysis revealed that the mutation frequencies of SLC39A1, SLC39A4, and SLC39A8 in pan-cancer patients were 4%, 6%, and 0.9%, respectively." (PMID 38230214, 2024). "In our study, the validation results showed that SLC39A1 was also highly expressed in cancer tissues, which indicate the role of SLC39A1 in the development of STAD." (PMID 37370118, 2023). "In contrast to ANPEP, AZGP1, the six metallothioneins and the network HUB genes, only one of the zinc-transporters (SLC39A1 - upregulated) showed any consistent differential expression between high- and low-grade cancer samples." (PMID 35707723, 2022). "For patients with LUAD, mRNA levels of SLC39A1, 3, 4, 5, 6, 7, 8, 9, 10, 11, 12 and 14 have significant difference in cancer tissues than in relative normal samples." (PMID 33535184, 2021). "For patients with LUAD, SLC39A1, 5, 7 and 11 were significantly highly expressed in cancer tissues than in normal lung tissues, and high expression of associated genes was associated with poorer prognosis." (PMID 33535184, 2021). "For patients with LUAD, mRNA levels of SLC39A1, 3, 4, 5, 6, 7, 9, 10, 11 and 14 were significant higher in cancer tissues than in relative normal samples, but SLC39A8 and SLC39A12 were expressed lower in cancer samples." (PMID 33535184, 2021). "The hub genes in modules with high correlation, such as ZAP70, RPS27A, GRP1, SLC39A1, APOBEC3G, and GZMA, could provide insights into the molecular mechanisms underlying cancer progression." (PMID 40395456, 2025). "The contribution of TMEM158, KIF18A, and SLC39A1 to cell proliferation or cancer progression was established already, but how exactly they integrate in the YAP signaling pathway is currently unknown." (PMID 33514403, 2021). "To gain further insights into the biological functions of SLC39A1, SLC39A4, and SLC39A8 in cancers, we utilized the LinkedOmics database to analyze their co-expression profiles in LIHC, CESC/PAAD, and KIRP, respectively." (PMID 38230214, 2024). "In light of the aberrant expression and significant roles played by SLC39A1, SLC39A4, and SLC39A8 genes in specific cancers, as well as the link between genetic alterations and cancer development, we further investigated the genetic alterations of these genes using the cBioPortal database." (PMID 38230214, 2024). "Additionally, immune infiltration analysis revealed that SLC39A1, SLC39A4, and SLC39A8 may function as immune regulators in cancers." (PMID 38230214, 2024). "However, the function and prognostic role of SLC39A1 in other cancers, especially in HCC have not been observed." (PMID 34615436, 2021). "Furthermore, while a functional genetic interaction between YAP and TRAM2, KIF18A, TMEM158, and SLC39A1 was never reported, the role of TMEM158, KIF18A, and SLC39A1 in cell proliferation or cancer progression was already established before." (PMID 33514403, 2021).
SLC39A1 also shares sentences with these, for which no sentence is quoted: infection (12 papers); Zinc deficiency (11); pancreatic cancer (4); adenocarcinoma (3); clear cell renal cell carcinoma (3); lung carcinoma (3); microsporidia infection (3); prostate tumors (3); viral infection (3); gastric tumor (2); Iron deficiency (2); liver cancer (2); lung adenocarcinoma (2); ovarian carcinoma (2); schizophrenia (2); Alzheimer disease (1); atherosclerosis (1); cervical squamous cell carcinoma (1); Cirrhosis (1); co-infection (1); colonic adenocarcinoma (1); colorectal cancer (1); endocervical adenocarcinoma (1); glioblastoma multiforme (1); hypertensive disease (1); Immunodeficiency (1); ischemic stroke (1); kidney disease (1); liver disease (1); lung disease (1).
A further 17 diseases each share a sentence with SLC39A1 in 1 paper.